VIP (vasoactive intestinal peptide)
Diseases named in the same sentence as VIP in open-access papers (continued):
Sharing a sentence is not in itself a finding about the gene and the disease.
migraine (continued). "There is, however, recent evidence that VIP, when administered as a prolonged infusion, may trigger migraine-like attacks in those with migraine and delayed headaches in healthy controls." (PMID 37569369, 2023). "As current results suggest that a prolonged vasodilation due to VIP might provoke migraine-like attacks, VIP blockade might be a potential target in migraine treatment." (PMID 37370051, 2023). "In recent years, the role of VIP in migraine attacks has been extensively studied." (PMID 37370051, 2023). "Finally, the associations of migraines with circadian or circannual rhythm-related neuropeptides other than PACAP, such as VIP, GRP, AVP, NMS, and DA, were described." (PMID 37373239, 2023). "VIP is a potential migraine biomarker, but shows little promise as a therapeutic agent." (PMID 37373239, 2023). "Overall, the search results suggest that VIP infusion may have a role in migraine pathophysiology, but further research is needed to fully understand its effects and potential therapeutic applications." (PMID 37998384, 2023). "Levels of VIP in blood and saliva, though elevated during a spontaneous migraine attack, undergo a significant reduction after triptan administration in adults with migraine." (PMID 37370051, 2023). "Many methods have been used to assess the ANS function of patients with migraine, including heart rate variability analysis, pupillary light reflex, analysis of salivary α-amylase level, and the detection of vasoactive intestinal peptide (VIP)." (PMID 35495060, 2022). "Expression of the related neuropeptides pituitary adenylate cyclase-activating peptide (PACAP) and vasoactive intestinal peptide (VIP) is well documented in several migraine-relevant structures, such as the trigeminal ganglia (TG), brainstem, cranial vasculature, and other cranial ganglia." (PMID 36430275, 2022). "As is true of AR, midfacial or nasal pain during migraine may be accompanied by the release of a variety of neuropeptides, such as histamine, substance P, NO, vasoactive intestinal peptide, TNF-α, and others." (PMID 36010131, 2022). "We investigated whether 2-h infusion of VIP caused alterations in plasma levels of the calcitonin gene-related peptide (CGRP) and whether any changes might be related to the induced migraine attacks." (PMID 35432170, 2022). "However, this argument has lost weight since a recent study with prolonged infusion of vasoactive intestinal peptide showed that it can induce migraine in patients." (PMID 35432179, 2022). "It would be interesting to investigate whether anti-CGRP therapies are able to prevent VIP-induced migraine attacks." (PMID 35432170, 2022). "Various recent studies demonstrated correlation with higher VIP levels and migraine." (PMID 35328439, 2022). "The following peptides have been implicated in migraine pathogenesis: adrenomedullin (ADM), amylin, calcitonin gene-related peptide (CGRP), pituitary adenylate cyclase-activating polypeptide (PACAP), and vasoactive intestinal polypeptide (VIP)." (PMID 35081902, 2022). "Collectively, we propose that PACAP, NPY, VIP, and nociceptin may play important roles in the pathogenesis of migraine." (PMID 34963819, 2021). "It has been proposed that VIP may play a role in triggering migraine chronification through vasodilation and nociceptor sensitization." (PMID 35002925, 2021). "Therefore, considering the different results of previous studies, it seems that the role of these factors should be appraised while introducing TRPV1, VIP, and PACAP as risk biomarkers for migraine progression." (PMID 35002925, 2021). "The VIP-induced migraine attacks mimicked patients’ spontaneous attacks." (PMID 34357396, 2021). "Our findings revisit the role of VIP in migraine pathogenesis and suggest that a prolonged arterial dilation might be involved in the initiation of migraine attacks." (PMID 34357396, 2021).
migraine (continued). "With our results of 71% migraine induction and prolonged STA dilation, the question arises whether we can explain VIP-induced migraine attacks by prolonged extracranial artery dilation." (PMID 34357396, 2021). "The dynamic changes in neuropeptides after stimulation suggest that CGRP, PACAP, NPY, VIP, and nociceptin may play a role in the pathogenesis of migraine." (PMID 34963819, 2021). "However, the changes in NPY, VIP, and nociception during migraine attacks and their relationship with migraine are still controversial." (PMID 34963819, 2021). "To date, it remains unclear whether the limited migraine-inducing property of VIP can be attributed to its equally limited vasodilatory response." (PMID 34357396, 2021). "In the present study, we found VIP had a 71% migraine induction rate." (PMID 34357396, 2021). "The role of VIP and/or a prolonged dilation of cranial arteries is critical in migraine initiation." (PMID 34488620, 2021). "We suggest that selective antagonists of VIP and its receptors could be potential targets for novel drugs for migraine." (PMID 34357396, 2021). "Parasympathetic activation could be able to sensitization of afferent nociceptors, this oversensitization and repeated stimulation might have a role in the transformation of EM to the chronic one, and VIP is assumed to have a role in migraine chronification." (PMID 35002925, 2021). "This may be reflected clinically where PACAP38 is a more potent migraine inducer than VIP." (PMID 39085771, 2024). "Therefore, solely targeting specific PACAP receptors might not be effective for migraine treatment, whereas focusing on the circulating PACAP ligand, mast cells, or circulating VIP may offer more promising targets for migraine therapy." (PMID 39085771, 2024). "Nonetheless, VIP may also be a potential drug target as migraine treatment." (PMID 39085771, 2024). "Interestingly, PACAP levels are elevated in migraine attacks, but VIP levels are only elevated if there are cranial autonomic sysmptoms associated, and both are elevated in the cranial circulation in cluster headache, a condition in which CAS are necessary for diagnosis." (PMID 38887982, 2024). "Furthermore, calcitonin gene-related peptide (CGRP), secreted by trigeminal nerves, and vasoactive intestinal peptide (VIP), secreted by parasympathetic nerves, could be involved in the pathophysiology of migraines and rhinosinusitis." (PMID 37240671, 2023). "Given that CAS are increasingly recognised in migraine and can present in the premonitory phase before headache, combined with emerging evidence that VIP may, in fact, be involved in the headache phase of migraine, VIP may emerge as a potential therapeutic target in migraine again in the future." (PMID 37569369, 2023). "VIP-mediated sensitization of trigeminal neurons can lead to hyperexcitability and increased responsiveness to noxious stimuli, which may contribute to the development and maintenance of chronic pain or migraine." (PMID 37998384, 2023). "However, recent findings hint that prolonged vasodilation from VIP might induce migraine-like episodes, suggesting that VIP blockage could be a promising migraine treatment." (PMID 37755358, 2023). "Serum VIP levels can also predict clinical outcomes following botulinum toxin therapy in migraine and may therefore be an interesting therapeutic biomarker in migraine." (PMID 37569369, 2023). "Therefore, a better understanding of the role of PACAP and other secretin family peptides, including VIP, in migraine pathogenesis could lead to new treatment options for this debilitating condition." (PMID 37998384, 2023). "A 2-h infusion of VIP provoked migraine, but the mechanisms remain unknown." (PMID 35432170, 2022).
migraine (continued). "Neuropeptides directly associated with pain or migraine from significantly differentially expressed neuropeptide prohormone genes include apelin (APLN), cortistatin (CORT), IGF2, neuromedin B (NMB), neuropeptide W (NPW), PDGFA and platelet-derived growth factor, D polypeptide (PDGFD), TAC4, and VIP." (PMID 35453627, 2022). "A most recent study has highlighted the potential use of PACAP, together with calcitonin gene related peptide (CGRP), in differentiating pediatric migraine from non-migraine headaches, while another recent study has shown the association between COVID-survival and VIP/PACAP plasma levels." (PMID 36204113, 2022). "VIP and its receptors could be potential targets for novel migraine drugs." (PMID 34357396, 2021). "The ability of PACAP, and not VIP, to cause allodynia in mice and migraine-like attacks in humans, supports the hypothesis that vasodilatation is not per se a major factor contributing to allodynia in mice and migraine pain in humans." (PMID 30764776, 2019). "However, the conclusion that vasodilation is an epiphenomenon based on the inability of VIP to induce migraine, may be a premature conclusion." (PMID 30127722, 2018). "The development and clinical testing of PACAP and/or VIP antagonists for migraine will need to carefully take into account how a widespread and/or uncontrolled blockade of these receptors might affect the known homeostatic activities of these endogenously-expressed peptides." (PMID 29536279, 2018). "In migraine, rhinitis, and vasomotor headaches, excessive parasympathetic activation mediated by the SPG (VIP/NO) and sensory nerves (CGRP) leads to pathological vasodilation, triggering pulsatile headaches, nasal congestion, and tissue edema." (PMID 41383224, 2025). "Other peptides being evaluated in the context of migraine are secretin peptides such as pituitary adenylate cyclase-activating polypeptide (PACAP) and vasoactive intestinal peptide (VIP), and to a lesser extent, other peptides in the same class." (PMID 39336867, 2024). "Neuropeptides, including CGRP, VIP, PACAP, and substance P, have key roles in the pathophysiology of migraine." (PMID 38612517, 2024). "Among the neuropeptides analyzed, only VIP exhibited higher levels in the Sp5C of the EM model and ACC of the CM model, highlighting significant differences between the two types of migraine." (PMID 38612517, 2024). "However, other studies have suggested that VIP infusions may actually provoke migraine attacks." (PMID 37998384, 2023). "The biomarker potential of VIP in migraines is comparable to that of PACAP; however, their involvement in migraine attacks is thought to be different." (PMID 37373239, 2023). "PACAP and VIP are likely involved in CAS mediation, but given these can present before headache in both migraine and cluster headache, activation of this reflex does not require headache." (PMID 37569369, 2023). "Pituitary adenylate cyclase-activating polypeptide (PACAP), structurally related to vasoactive intestinal peptide (VIP), is one of the important mediators in the pathogenesis of migraine and is known to dilate cranial arteries and induce headache and migraine." (PMID 37231350, 2023). "Receptor-wise, the main difference between PACAP38 and VIP is the over 1000-fold higher affinity of PACAP38 to the PAC1 receptor, which positions the PAC1 receptor as a potential novel target for migraine treatment." (PMID 37370051, 2023). "Subsequently, a rat model of migraine using repeated electrical stimulation of the trigeminal ganglion revealed increased NPY levels (as well as CGRP, PACAP, and VIP) in both trigeminal ganglion and blood." (PMID 37569369, 2023). "The mediators released from nociceptors and MCs during bidirectional communication, such as CGRP, PACAP-38, VIP, PGI2, serotonin, and others, are recognized as compounds that likely contribute to migraine." (PMID 37232078, 2023).
migraine (continued). "While intestinal secretion of VIP increases motility and lowers blood pressure due to a vasodilating effect, hypothalamic secretion of PACAP induces, e.g., migraines." (PMID 35203615, 2022). "In addition to investigating the role of different receptor subtypes and splice variants in migraine, future studies utilizing these characterized antibodies could include whether PACAP or VIP knockout stimulates the differential expression of receptor subtypes in migraine-related structures." (PMID 36430275, 2022). "There is currently no clinical data available describing the effects of blocking VIP, VPAC1, or VPAC2 activity in migraine." (PMID 36430275, 2022). "Several other neuropeptides involved in migraine, such as pituitary adenylate cyclase activating polypeptide (PACAP), vasoactive intestinal peptide (VIP), neuropeptide Y (NYP), and nociception, have also been studied." (PMID 34963819, 2021). "Background and Objective: Vasoactive intestinal polypeptide (VIP) and pituitary adenylate cyclase-activating polypeptides (PACAPs) are structurally and functionally related yet different in their migraine-inducing properties." (PMID 34488620, 2021). "Mentioned factors can affect VIP and PACAP level, and also other possibly involved factors in migraine pathogenesis at the time of sampling." (PMID 35002925, 2021). "In this study, to investigate some molecular alterations involved in migraine chronification, serum levels of TRPV1, VIP, and PACAP were evaluated in patients with episodic and CM, and also healthy individuals." (PMID 35002925, 2021). "Using this approach, a total of 6 prohormones were found to correlate with migraine and/or OIH conditions from their respective controls: Vasoactive Intestinal peptide (VIP), PACAP, thyrotropin-releasing hormone prohormone (proTRH), PENK, SCG and proSAAS." (PMID 31649062, 2019). "Our experiments revealed that EA significantly reduced the DES-induced overexpression of CGRP, SP, VIP, PACAP, NO and ET-1 in recurrent migraine model rats." (PMID 31217804, 2019). "The potent headache provoking property of PACAP1–38 in comparison with the poor effect of VIP, suggests PAC1- R to be an interesting target for migraine treatment." (PMID 29460121, 2018). "Sixteen out of 22 patients (73%) reported delayed migraine-like attacks following PACAP38 infusion, whereas only 4 out of 22 (18%) did so after VIP infusion." (PMID 29453754, 2017). "The vasodilatory actions of VIP and PACAP in brain arteries have been demonstrated in the context of migraine." (PMID 27357191, 2016). "Increased peripheral blood VIP levels have been detected in chronic migraine, and intravenous administration of PACAP has been shown to induce migrainous headache in migraine patients, suggesting that both transmitters are related to migraine pathophysiology." (PMID 26156114, 2015). "Therefore, the relationships of other neuropeptides (e.g., VIP, PACAP, and substance P) with the pathogenesis of migraine must be elucidated." (PMID 38612517, 2024). "The skin reaction to local injection of PACAP-38 and VIP showed increased flow, wheal and flare of both compounds and thus, did not explain why PACAP-38 and not VIP caused migraine." (PMID 38902612, 2024). "VIP levels increase in patients with GERD and may promote vasodilation and mast cell degranulation in the dura mater, leading to migraine." (PMID 38990854, 2024). "VIP also leads to a marked dilation of cranial arteries; however, it does not trigger migraine attacks in migraineurs, as demonstrated in a randomized controlled trial." (PMID 37240671, 2023). "In addition, there is evidence that migraine patients with CAS respond better to triptans, and VIP serum levels were reduced after triptans administration." (PMID 36832077, 2023). "In the SPG, VIP is co-expressed with CGRP and PACAP, and this may provide an interaction between the sensory and parasympathetic systems in migraine." (PMID 37569369, 2023).
migraine (continued). "Immunohistochemical studies subsequently demonstrated VIP-ergic fibres in central nervous system areas important in migraine, such as the PAG and NRM, although, interestingly, not in the TNC or C1 and C2." (PMID 37569369, 2023). "Within the complex pathophysiology of migraine, among others, activation of trigeminovascular neurons results in the release of substances such as calcitonin gene-related peptide (CGRP), substance P, nitrous oxide, vasoactive intestinal peptide and serotonin." (PMID 38110925, 2023). "By contrast, experimental human models (e.g., hypoxia and VIP infusion) did not report any significant change in CGRP blood plasma levels in migraine patients." (PMID 36982428, 2023). "The role in migraine pathophysiology of two of them, PACAP and VIP, has been extensively studied." (PMID 37569648, 2023). "A phase 2 clinical trial investigated the effects of a long-lasting infusion of VIP on headaches, cranial hemodynamics, and autonomic symptoms in episodic migraine patients without aura." (PMID 37998384, 2023). "This difference in the induction of migraine-like attacks between VIP and PACAP was attributed to the non-involvement of VIP in a potent migraine-inducing pathway, unlike PACAP." (PMID 37373239, 2023). "During VIP infusion, mixed effects analysis revealed a significant increase in plasma CGRP (p = 0.027) at T30 (vs. T180, adjusted p-value = 0.039) and T60 (vs. T180, adjusted p-value = 0.027) in patients with migraine." (PMID 35432170, 2022). "While the current study design and the number of enrolled patients with migraine were sufficient to identify a direct effect of VIP on plasma CGRP, new studies will clarify whether this is of significance for migraine." (PMID 35432170, 2022). "Our findings suggest that a 2-hour infusion of VIP induced migraine attacks in patients with migraine without aura." (PMID 34357396, 2021). "To investigate the dynamic changes of the neuropeptides in the rat model of migraine, we measured the mRNA and protein expression of CGRP, PACAP, NPY, VIP, and nociceptin in the TG on the stimulated side and the protein levels of these neuropeptides in the plasma." (PMID 34963819, 2021). "Notably, it was found that electroacupuncture (EA) treatment significantly decreased concentrations of CGRP, VIP, and PACAP in rat models of recurrent migraines." (PMID 33653014, 2021). "In contrast, VIP-induced vasodilation of the cranial arteries failed to trigger migraine attacks in patients with migraine and only produced a mild, short lasting headache in healthy subjects." (PMID 35295486, 2021). "Specifically, for migraine: VIP and SCG2 in the NAc, PACAP, SCG1, and proTRH in the PAG, and PENK in the DH; and for OIH: VIP in the NAc, SCG, proSAAS and PACAP in the PAG, and SCG in the TN and DH, were significantly changed between the treated and control groups (p ≤ 0.1) in both cohorts." (PMID 31649062, 2019). "As VIP does not induce migraine-like attacks, it is assumed that PACAP’s actions are mediated by PAC1 receptor activation." (PMID 30088106, 2018). "Both migraine and TACs are believed to share a common pathophysiology comprising of the activation of the trigeminovascular system and involvement of neuroactive peptides such as calcitonin gene-related peptide (CGRP), vasoactive peptide (VIP) and glutamate." (PMID 25902798, 2015). "Their possible predictive value received further support from a study describing detectable serum vasoactive intestinal polypeptide (VIP), the biochemical marker of parasympathetic activation, in the external jugular blood in one-half of migraine patients who responded to rizatriptan." (PMID 22460943, 2012). "No studies have focused on selective VIP blockage for migraine treatment yet." (PMID 37755358, 2023). "It remains unclear whether the lack of migraine induction can be attributed to the only transient vasodilatory response after a 20-min infusion of VIP." (PMID 37998384, 2023).